DHX30 (DExH-box helicase 30)
Description:
RNA-dependent helicase. Plays an important role in the assembly of the mitochondrial large ribosomal subunit. Required for optimal function of the zinc-finger antiviral protein ZC3HAV1 (By similarity). Associates with mitochondrial DNA. Involved in nervous system development and differentiation through its involvement in the up-regulation of a number of genes which are required for neurogenesis, including GSC, NCAM1, neurogenin, and NEUROD (By similarity).
Synonyms: DDX30; KIAA0890; FLJ11214; NEDMIAL; RETCOR
Tractability: PROTAC: ubiquitination databases record sites on it; its protein half-life has been measured; a small molecule that binds it is known.
Target class: Enzyme; Hydrolase
Gene: Protein-coding gene on chromosome 3 (47,802,641 to 47,851,617, forward strand). Ensembl gene ENSG00000132153.
Subcellular location: Cytoplasm; Mitochondrion; Mitochondrion matrix, mitochondrion nucleoid
Subcellular location (Human Protein Atlas): Mitochondria; Cytosol
Gene Ontology:
Molecular function: ATP hydrolysis activity; chromatin binding; double-stranded RNA binding; protein binding; RNA binding; RNA helicase activity; DNA helicase activity; G-quadruplex RNA binding; ATP binding; nucleic acid binding
Biological process: mitochondrial large ribosomal subunit assembly; central nervous system development
Cellular component: cytoplasm; cytosol; mitochondrial matrix; mitochondrial nucleoid; mitochondrion; ribonucleoprotein granule; nucleus
Genetic constraint (gnomAD): Loss-of-function variants: 4 observed, 113.99 expected, observed/expected ratio (o/e) 0.0351, 90% interval 0.016 to 0.08. The upper end of that interval is the gene's LOEUF score, 0.08, which puts it in group 1 of 6, group 1 being the genes least tolerant of losing a copy. Missense variants: 838 observed, 1,593.7 expected, observed/expected ratio (o/e) 0.53, 90% interval 0.5 to 0.56. Synonymous variants: 674 observed, 654.96 expected, observed/expected ratio (o/e) 1.03, 90% interval 0.96 to 1.1.
Gene-disease validity (ClinGen):
ClinGen rates the evidence that DHX30 causes each of these diseases.
neurodevelopmental disorder with severe motor impairment and absent language (autosomal dominant): Definitive. A complex neurodevelopmental disorder caused by variation in DHX30.
Homologues: Orthologues: mouse Dhx30 (98% identical), chimpanzee DHX30 (97% identical), macaque DHX30 (97% identical), dog DHX30 (96% identical), rabbit DHX30 (95% identical), rat Dhx30 (95% identical), pig DHX30 (95% identical), guinea pig DHX30 (95% identical), tropical clawed frog dhx30 (55% identical), zebrafish dhx30 (47% identical). Paralogues in human: DHX57 (27% identical), DHX9 (25% identical), DHX29 (25% identical), DHX36 (24% identical), YTHDC2 (24% identical), DHX34 (20% identical), DHX16 (19% identical), DHX37 (19% identical), TDRD9 (18% identical), DHX8 (18% identical), DHX38 (17% identical), DHX15 (17% identical), and 6 more.
Diseases named in the same sentence as DHX30 in open-access papers:
DHX30 is named in the same sentence as 22 diseases in open-access papers, as found by Europe PMC text mining. Sharing a sentence is not in itself a finding about the gene and the disease. The quoted sentences say what the papers report.
developmental delay (4 papers, 2021 to 2022). "The missense mutations in the DHX30 gene have been identified as a genetic cause of neurodevelopmental disorders characterized by global developmental delay, intellectual disability, severe speech impairment, and gait abnormalities." (PMID 36163369, 2022). "Mutations in another transcript in this set, DHX30, leads the protein to localize to stress granules and causes translational repression, and are associated with developmental delays and intellectual disability." (PMID 36018791, 2022). "Recently, de novo missense mutations were identified in DHX30 in twelve unrelated patients affected by global developmental delay (GDD), intellectual disability (ID), severe speech impairment, and gait abnormalities." (PMID 34503222, 2021). "Previously, we reported 12 unrelated individuals with global developmental delay (GDD), intellectual disability (ID) accompanied by severe speech impairment and gait abnormalities, harboring one of six different de novo missense variants located within highly conserved HCMs of DHX30." (PMID 34020708, 2021).
Intellectual disability (4 papers, 2019 to 2024). "DHX30 loss-of-function in mouse is embryolethal by day 9.5, and missense mutations within its core helicase produce intellectual disability and facial anomalies." (PMID 30973878, 2019). "Moreover, it is striking that mutations in other DEAD box RNA helicases, such as DHX30, DDX3X, or DDX59, all cause intellectual disability or other neurodevelopmental disorders." (PMID 38536035, 2024).
breast carcinoma (2 papers, 2019 to 2021). "Transient DHX30 silencing was also performed in the breast cancer-derived MCF7 cells and shown to be effective and isoform specific." (PMID 34503222, 2021). "We discovered that there are three genes (DHX30, USP19, and RBM15B), which are highly positively correlated with BAP1 in both black and white breast cancer patients." (PMID 30716094, 2019). "DHX30 has the highest positive correlation with BAP1 in black-alive and white-dead categories, while USP19 has the maximum positive correlation with BAP1 in black-dead and white-alive breast cancer categories." (PMID 30716094, 2019).
asthma (1 paper, 2021). "TNRC6B and MET were hypermethylated in both of our ACO patients and the asthma patients in previous EWAS, while DHX30, SFXN, C19orf28, and CLCN7 were hypomethylated." (PMID 33658578, 2021).
Ataxia (1 paper, 2022). Ataxia refers to impaired coordination of voluntary muscle movement. "DHX30 mutations lead to NEDMIAL with ataxia and psychomotor retardation." (PMID 35954215, 2022).
autism spectrum disorder (1 paper, 2023). A spectrum of developmental disorders that includes autism, and Asperger syndrome. "In summary, our study has revealed the involvement of four known genes (DEAF1, CLCN3, KMT2C, and DHX30) as well as two novel genes (TRPC4 and SCFD2) in autism spectrum disorder across six families from Qatar." (PMID 38025430, 2023).
breast invasive carcinomas (1 paper, 2019). "In patients with breast invasive carcinomas, BAP1 is highly positively correlated with NSG00000132153.13 (DHX30), ENSG00000259956.1 (RBM15B), and ENSG00000172046.17 (USP19), in all four categories." (PMID 30716094, 2019).
cerebral infarction (1 paper, 2022). An ischemic condition of the brain, producing a persistent focal neurological deficit in the area of distribution of the cerebral arteries. "To investigate the localization of DHX30 in motor neurons of ALS-FUS patients, we performed immunohistochemistry using consecutive sections within the anterior horn of the lumbar spinal cord from an ALS-FUS patient with FUS P525L mutation and a control patient with cerebral infarction." (PMID 36163369, 2022).
endometrial cancer (1 paper, 2021). Primary or metastatic malignant neoplasm involving the endometrium (mucous membrane that lines the endometrial cavity). "However, endometrial cancer patients with downregulated PTEN and DHX30 tended to have worse prognosis, compared to patients where this is not the case; this suggests that not all the SL interactions identified by CLIP are supported by the survival analyses in the patient cohorts." (PMID 33750001, 2021).
osteosarcoma (1 paper, 2021). A usually aggressive malignant bone-forming mesenchymal neoplasm, predominantly affecting adolescents and young adults. "Using human fibroblasts and osteosarcoma cells, it was shown that DHX30 could also play an important role in the mitochondria." (PMID 34503222, 2021). "The analysis of DHX30 stable or transient silencing (siDHX30-C or siDHX30C+M) was extended to U2OS, osteosarcoma-derived cells that express relatively high levels of DHX30." (PMID 34503222, 2021).
pancreatic cancer (1 paper, 2025). "Immunohistochemical results showed that among the 8 CRGs: CEP55, FAM111B, MRPL3, MET, and KNSTRN had higher protein expression in pancreatic cancer tissues, while on the contrary, the protein expression of DHX30 in normal pancreas was significantly higher than that in pancreatic cancer tissues." (PMID 40677006, 2025).
virus infection (1 paper, 2024). "Previous studies have shown that DHX30 bound SVV dsRNA and did not inhibit the activity of SVV 5’UTR, which may have an impact on virus infection." (PMID 39547416, 2024).
X-linked intellectual disability syndrome (1 paper, 2023). "Furthermore, DHX30 forms an interaction with CUL4B, which is associated with X-linked intellectual disability syndrome." (PMID 38025430, 2023).
neurodevelopmental disorder (10 papers, 2021 to 2025). A behavioral and cognitive disorder with onset during the developmental period that involves impaired or aberrant development of intellectual, motor, or social functions. "Missense variants in DHX30 are associated with Neurodevelopmental disorder with variable motor and language impairment (NEDMIAL, #617804), with loss-of-function variants causing a milder phenotype." (PMID 39149612, 2024). "We aimed to define the clinical and variant spectrum and to provide novel molecular insights into the DHX30-associated neurodevelopmental disorder." (PMID 34020708, 2021). "Here, we highlight the efforts of Mannucci and colleagues to define a novel molecular subtype of neurodevelopmental disorder associated with mutations in DHX30 and characterize location-specific mutational effects in cell culture and zebrafish models." (PMID 34099044, 2021). "The identification of 25 affected individuals has expanded the clinical and genetic spectrum of the DHX30-associated neurodevelopmental disorder." (PMID 34020708, 2021). "We have previously established de novo, heterozygous, DHX30 missense variants, affecting highly conserved residues within its HCMs, as a cause of a severe neurodevelopmental disorder, Neurodevelopmental disorder with variable motor and language impairment (NEDMIAL; #OMIM 617804)." (PMID 39149612, 2024). "Therefore, we suggest referring to these conditions as DHX30-associated neurodevelopmental disorders in the future." (PMID 34020708, 2021). "Therefore, based on the clinical and molecular findings we suggest a classification in two DHX30-associated neurodevelopmental disorder subtypes." (PMID 34020708, 2021). "Taken together, our data indicate that dhx30 KO zebrafish have a social behavioral deficit with altered sleep-wake activity, which is consistent with findings in DHX30-related neurodevelopmental disorders." (PMID 34020708, 2021). "Our study has allowed further delineation of the clinical spectrum of DHX30-related neurodevelopmental disorders through analysis of 25 novel affected individuals, partially facilitated by the use of a social media-based family support group." (PMID 34020708, 2021). "Here, we performed clinical, genetic, and functional analyses to provide further understanding of DHX30-related neurodevelopmental disorders through the identification of 25 previously unreported individuals." (PMID 34020708, 2021). "The importance and functional relevance of certain SF2 RHs in human neurodevelopment is demonstrated by the identification of pathogenic germline variants in DDX3X, DDX6, DHX30, and DDX5 in individuals with neurodevelopmental disorders." (PMID 34020708, 2021). "DHX30, along with other SF2 members such as DDX3X, DDX6, and DDX59, have been strongly implicated in neurodevelopmental disorders." (PMID 34099044, 2021). "DHX30 is an ATP‐dependent RNA helicase that participates in RNA metabolism, including in mitochondria, and has been implicated in a neurodevelopmental disorder with severe motor impairment and absence of language (NEDMIAL)." (PMID 40873389, 2025). "The observed social behavioral deficits and altered sleep-wake activity are similar to the findings in zebrafish models of other neurodevelopmental disorders, and to some extent recapitulate the clinical findings in individuals affected by the DHX30-related neurodevelopmental disorder." (PMID 34020708, 2021). "Compared to wild-type and heterozygous siblings, the homozygous mutants displayed significantly less activity during the day and more nocturnal activity, mimicking somewhat the sleep disturbances in individuals affected by a DHX30-related neurodevelopmental disorder." (PMID 34020708, 2021). "We next examined whether dhx30-deficient zebrafish exhibit abnormal sleep-wake activity and social behaviors, similar to those recently observed in a zebrafish model of the NR3C2-related neurodevelopmental disorder." (PMID 34020708, 2021).
infection (3 papers, 2020 to 2022). The state of being infected such as from the introduction of a foreign agent such as serum, vaccine, antigenic substance or organism. "For SVA, to antagonize the anti-SVA effects of DHX30, during the infection of SVA, the 3C protein of SVA interacts with DHX30 and cleaves DHX30 at the Q220 site." (PMID 36618383, 2022).
cancer (2 papers, 2021 to 2025). A tumor composed of atypical neoplastic, often pleomorphic cells that invade other tissues. "The results showed that except for DHX30, mRNA expression levels of other 7 genes in cancer cells were higher than those in normal cells." (PMID 40677006, 2025). "Exploiting RIP, eCLIP, and gene expression data, we identified fourteen mitoribosome transcripts we propose as direct DHX30 targets that can be used to explore the prognostic value of this mechanism in cancer." (PMID 34503222, 2021). "We thus propose DHX30 as a potential vulnerability in cancer cells that could be exploited to develop novel therapeutic strategies." (PMID 34503222, 2021). "Both of these functions suggest that DHX30 could be a modifier of cancer cell properties, potentially impacting clinical variables." (PMID 34503222, 2021). "These preliminary analyses suggest that a functional signature could be developed to predict aggressiveness in cancer types where DHX30 appears to stimulate mitoribosomal proteins expression." (PMID 34503222, 2021). "Targeting DHX30 could, thus, expose a vulnerability in cancer cells." (PMID 34503222, 2021). "Depleting DHX30 in HCT116 cells enhanced global translation but reduced cell proliferation, as also confirmed in two other cancer cell line models." (PMID 34503222, 2021). "Then, choosing MRPL11 (UL11m) that was previously evaluated in cancer cells and MRPS22 (mS22) as representatives of the large and small mitoribosome subunits, we observed that the DHX30-depleted cells showed reduced expression of these two genes at both the RNA and protein levels." (PMID 34503222, 2021).
DHX30 also shares sentences with these, for which no sentence is quoted: Angelman syndrome (1 paper); autism (1); Hydrocephalus (1); microcephaly (1); prostate carcinoma (1); Rett syndrome (1).